OR5H8 (olfactory receptor family 5 subfamily H member 8 (gene/pseudogene))
Description:
Odorant receptor.
Synonyms: formerly OR5H8P
Gene: Protein-coding gene on chromosome 3 (98,306,752 to 98,312,843, forward strand). Ensembl gene ENSG00000232535.
Subcellular location: Cell membrane
Homologues: Orthologues: rat Or5h26 (65% identical), dog OR5H13 (65% identical), mouse Or5h26 (65% identical), dog OR5H9 (64% identical), rat Or5h26b (64% identical), dog OR5H12 (63% identical), dog OR5H16 (63% identical), mouse Or5h25 (62% identical), dog OR5H11 (62% identical), mouse Or5h18 (62% identical), mouse Or5h23 (62% identical), mouse Or5h17 (61% identical), and 12 more. Paralogues in human: OR5H14 (67% identical), OR5H1 (67% identical), OR5H2 (66% identical), OR5H15 (65% identical), OR5H6 (65% identical), OR5AC2 (48% identical), OR5K1 (43% identical), OR5K4 (43% identical), OR5K2 (43% identical), OR5K3 (41% identical), OR5B12 (40% identical), OR5AP2 (40% identical), and 84 more.